IGHV4-34 (immunoglobulin heavy variable 4-34)
Description:
V region of the variable domain of immunoglobulin heavy chains that participates in the antigen recognition. Immunoglobulins, also known as antibodies, are membrane-bound or secreted glycoproteins produced by B lymphocytes. In the recognition phase of humoral immunity, the membrane-bound immunoglobulins serve as receptors which, upon binding of a specific antigen, trigger the clonal expansion and differentiation of B lymphocytes into immunoglobulins-secreting plasma cells. Secreted immunoglobulins mediate the effector phase of humoral immunity, which results in the elimination of bound antigens. The antigen binding site is formed by the variable domain of one heavy chain, together with that of its associated light chain. Thus, each immunoglobulin has two antigen binding sites with remarkable affinity for a particular antigen. The variable domains are assembled by a process called V-(D)-J rearrangement and can then be subjected to somatic hypermutations which, after exposure to antigen and selection, allow affinity maturation for a particular antigen.
Synonyms: IGHV434; VH
Tractability: Antibody: its Gene Ontology location is reachable by antibodies, with high confidence; UniProt places it where antibodies can reach, with medium confidence; UniProt predicts a signal peptide or a membrane-spanning region.
Gene: Immunoglobulin variable (V) gene on chromosome 14 (106,373,663 to 106,374,145, reverse strand). Ensembl gene ENSG00000211956.
Subcellular location: Secreted; Cell membrane
Pathways (Reactome):
Immune System: Antigen activates B Cell Receptor (BCR) leading to generation of second messengers; CD22 mediated BCR regulation; Classical antibody-mediated complement activation; FCERI mediated Ca+2 mobilization; FCERI mediated MAPK activation; FCERI mediated NF-kB activation; FCGR activation; Fc epsilon receptor (FCERI) signaling; Immunoregulatory interactions between a Lymphoid and a non-Lymphoid cell; Initial triggering of complement; Regulation of Complement cascade; Regulation of actin dynamics for phagocytic cup formation; Role of LAT2/NTAL/LAB on calcium mobilization; Role of phospholipids in phagocytosis
Disease: FCGR3A-mediated IL10 synthesis; FCGR3A-mediated phagocytosis; Potential therapeutics for SARS
Hemostasis: Cell surface interactions at the vascular wall
Vesicle-mediated transport: Scavenging of heme from plasma
Gene Ontology:
Molecular function: antigen binding
Biological process: immune response; immunoglobulin mediated immune response
Cellular component: extracellular region; plasma membrane
Genetic constraint (gnomAD): Missense variants: 63 observed, 30.95 expected, observed/expected ratio (o/e) 2.04. Synonymous variants: 22 observed, 12.39 expected, observed/expected ratio (o/e) 1.78, 90% interval 1.21 to 1.96.
Homologues: Paralogues in human: IGHV4-39 (86% identical), IGHV4-59 (85% identical), IGHV4-61 (85% identical), IGHV4-31 (84% identical), IGHV4-4 (84% identical), IGHV4OR15-8 (82% identical), IGHV4-28 (80% identical), IGHV6-1 (56% identical), IGHV3-11 (50% identical), IGHV2-26 (50% identical), IGHV2-5 (48% identical), IGHV2-70 (48% identical), and 65 more.
Diseases named in the same sentence as IGHV4-34 in open-access papers:
IGHV4-34 is named in the same sentence as 4 diseases in open-access papers, as found by Europe PMC text mining. Sharing a sentence is not in itself a finding about the gene and the disease. The quoted sentences say what the papers report.
Autoimmunity (1 paper, 2012). The occurrence of an immune reaction against the organism's own cells or tissues. "In addition to IGHV4-34 involvement in autoimmunity, a profound counterselection against IGHV4-34 among normal peripheral B-cell subsets (GC, memory, and PC) has also been documented in healthy subjects." (PMID 22558161, 2012).
diffuse large B-cell lymphoma (1 paper, 2025). "IGHV4–34 has also been identified in mucosa-associated lymphoid tissue (MALT) lymphoma and diffuse large B-cell lymphoma (DLBCL), pointing toward a shared pathogenesis in IGHV4-34-positive B-cell tumors." (PMID 40900797, 2025).
IGHV4-34 also shares sentences with these, for which no sentence is quoted: chronic lymphocytic leukemia (1 paper); systemic lupus erythematosus (1).